GAST (gastrin)
Diseases named in the same sentence as GAST in open-access papers (continued):
Sharing a sentence is not in itself a finding about the gene and the disease.
anemia (11 papers, 2008 to 2024). A reduction in the number of red blood cells, the amount of hemoglobin, and/or the volume of packed red blood cells. "The patient also had iron deficiency anemia and thyroid dysfunction, elevated gastrin, and decreased pepsinogen I (PG I) and PG I/II." (PMID 39830375, 2024). "Similar to Family 1, the patients had elevated fasting blood gastrin levels and iron deficiency anemia." (PMID 35205297, 2022). "They recommend that patients with risk factors for AIG and/or refractory B12 or iron deficiency anemia be tested for PCA, IFA, serum gastrin, and anti-Helicobacter pylori antibodies as a way to identify patients appropriate for endoscopy." (PMID 38474790, 2024). "P. Laboratory findings showed anemia, diminished iron, ferritin, and vitamin B12, with increased gastrin and anti-parietal cell antibody levels." (PMID 26681999, 2015). "Isolated diffuse hyperplasic gastric polyposis with normal gastrin level is a rare entity and can present with severe anemia." (PMID 18755016, 2008). "In addition to congenital hearing loss and cardiac symptoms, some individuals with JLNS have also been found to have anemia and elevated levels of the hormone gastrin." (PMID 27446933, 2016). "Laboratory data demonstrated mild anemia (hemoglobin 11.1 g/dL), elevated BUN (33.1 mg/dL) and normal gastrin (25 pg/mL), suggesting the possible presence of gastrointestinal bleeding." (PMID 21714884, 2011). "Laboratory findings showed mild anemia (hemoglobin 12.0 g/dL), elevated blood urea nitrogen (BUN) (27.9 mg/dL) and normal gastrin (150 pg/mL)." (PMID 21714884, 2011). "If a paediatric patient presents with symptoms such as anaemia, reduced vitamin B12 levels, recurrent urticaria with no other detectable aetiology, positive APCA, and elevated gastrin levels, AAG should be considered a possible cause of these skin manifestations." (PMID 37947925, 2024). "The presence of risk factors and/or of therapy-resistant B12 or iron-deficient anemia, in the absence of aetiological agents that can be directly correlated, is clinical criteria that suggest to test for PCA, IFA, and gastrin as immunological and biochemical markers of AIG." (PMID 23251219, 2012).
Constipation (11 papers, 2014 to 2023). Infrequent or difficult evacuation of feces. "Collectively, our results suggest that IBS constipation patients experience reductions in the gastric emptying rate and elevated plasma gastrin levels." (PMID 37296188, 2023). "Previous studies have reported that the concentrations of CCK and gastrin were significantly increased in the Lop-induced constipation model after exposure to spicatoside A as compared to the Lop+Vehicle-treated group." (PMID 34885790, 2021). "Therefore, the improvement in the ENS function through the Urd and AEtLP treatments during C3-deficiency-induced constipation is reflected in the regulation of CCK and gastrin concentrations." (PMID 37958740, 2023). "Thus, the results of the present study provide the first evidence that the defecation stimulation effects of Pt are strongly correlated with changes in CCK and gastrin concentrations in the Lop-induced constipation model." (PMID 34885790, 2021). "To investigate whether the defecation stimulation effects of TEE are accompanied by alterations in regulating the secretion of GI hormones of constipation rats, we measured the concentrations of CCK, gastrin and SS in the colon homogenate of Lop-induced constipation rats after TEE treatment." (PMID 33626068, 2021). "Studies have reported that GI hormones such as motilin (MTL), cholecystokinin (CCK), gastrin (Gas), and SP are significantly decreased while SS and VIP are increased in constipation-induced rats." (PMID 36145085, 2022). "Regulation of gastrointestinal hormones, such as cholecystokinin (CCK), gastrin (GAS), somatostatin (SS) and motilin (MTL), may also be another important mechanism for improving the symptoms of LOP-induced constipation in animal models after ACCE administration." (PMID 35518898, 2019).
multiple endocrine neoplasia type 1 (11 papers, 2012 to 2025). An autosomal dominant tumor predisposition syndrome caused by pathogenic variants in the MEN1 gene, characterized by an increased risk of tumors of the parathyroid glands, pituitary gland, and foregut neuroendocrine tumors (most commonly pancreatic islet cells). "Type 2 is linked to Zollinger-Ellison syndrome in the context of multiple endocrine neoplasia type 1 (MEN-1), while type 3 corresponds to sporadic, gastrin-independent tumors with a more aggressive behavior and higher metastatic potential." (PMID 40673288, 2025). "The levels of PTH, serum calcium, glucagon and gastrin were measured, which were all in normal range excluding the clinical diagnosis of multiple endocrine neoplasia type 1." (PMID 38093965, 2023). "Type 2 gastric carcinoid tumors are gastrin-producing tumors (Zolliger–Ellison syndrome) and usually occur in the context of multiple endocrine neoplasia type 1 (MEN-1)." (PMID 36979851, 2023). "Patients' hypergastrinemia does not result from parietal cell loss, but is due to gastrin secreting G cell neoplasia in association with ZES and/or multiple endocrine neoplasia type 1 (MEN-1)." (PMID 23316222, 2012). "Type 2 gastric carcinoids occur in ZES patients, primarily in patients with multiple endocrine neoplasia type 1(MEN1/ZES), comprise 5–6% of all gastric carcinoids, are well-differentiated, are also gastrin-dependent, and malignant in 10–30%." (PMID 31623145, 2019).
chronic kidney disease (9 papers, 2013 to 2025). Impairment of the renal function secondary to chronic kidney damage persisting for three or more months. "Gastrointestinal signs in patients with chronic kidney disease (CKD) have been attributed to higher circulating uremic toxins and decreased renal clearance of gastrin, a hormone that, in excess, can cause gastric hyperacidity and ulceration." (PMID 41007911, 2025). "Some of these cases were attributed to chronic kidney disease, which is known to influence gastrin concentrations because gastrin is partially cleared from circulation by renal metabolism." (PMID 34867785, 2021). "Patients with chronic renal failure have 2- to 3-fold higher serum gastrin levels because the kidneys are responsible for clearing gastrin." (PMID 27840636, 2016). "End-stage renal disease (ESRD) patients have higher than normal circulating levels of gastrin, probably due to decreased renal clearance of gastrin, increased gastric G cell density, and decreased inhibition secondary to diminished somatostatin levels." (PMID 25698559, 2015). "Patients with chronic renal insufficiency not only present higher circulating levels of gastrin and gastric dysmotilty, but also make use of a great amount of drugs for the treatment of their comorbidities." (PMID 24139477, 2013).
colorectal tumors (9 papers, 1989 to 2023). "We have previously demonstrated the trophic properties of gastrin in mouse colorectal tumour cells (MC-26), in which the peptide caused a significant incorporation of [3H]thymidine at 24 and 48 h." (PMID 15798764, 2005). "Several studies have shown a relationship between colorectal tumors and gastrin 25, 26, while others disagreed 27-29." (PMID 36794160, 2023). "Gastric H. pylori infection induces colorectal tumors by regulating the expression of serum gastrin, and then hypergastrinemia accelerates the proliferation of gastrointestinal mucosal cells." (PMID 36046645, 2022). "Since it had previously been reported that serum gastrin levels are elevated in colorectal tumors, she decided to begin her investigation in that tumor." (PMID 34926305, 2021). "An important target for the therapy of pancreatic, gastritic, and colorectal tumors is gastrin, a peptide hormone, whose activity can be blocked by antibodies that recognize gastrin as their epitope, delaying tumor growth." (PMID 26835447, 2015). "The gastrin system exists in an autocrine proliferative loop in colorectal tumor." (PMID 32210918, 2020). "We thus sought to determine whether gastrin might regulate β-catenin expression in colorectal tumour cells." (PMID 15798764, 2005). "Finally, G-17 prolonged the τ1/2 of β-catenin protein, demonstrating that gastrin appears to exert its mitogenic effects on colorectal tumour cells, at least in part, by stabilising β-catenin." (PMID 15798764, 2005). "As gastric and colorectal tumour cells show a trophic response to gastrin, antagonists of the gastrin receptor may prevent this effect causing tumour stasis." (PMID 2713241, 1989). "Co-expression of gastrin and CCK2R message is significantly increased in colorectal tumor." (PMID 32210918, 2020).
H. pylori (9 papers, 2009 to 2025). "Helicobacter infection is strongly associated with the induction of a strong Th1-type inflammatory response, with high levels of Ifnγ, which induces expression of other inflammatory mediators such as iNOS and Cox-2, and also circulating growth factors such as gastrin." (PMID 19317916, 2009). "Helicobacter pylori (H. pylori, HP) infection, pepsinogen I, gastrin-17, and the number of lesions were found to be independent rick factors of the model." (PMID 35665336, 2022). "The effect of H. pylori-infection on physiological parameters (pH, gastrin) in the stomach was analyzed over time." (PMID 19270747, 2009).
Iron deficiency anemia (9 papers, 2008 to 2024). "Subsequent serum evaluation was remarkable for an elevated fasting gastrin level and an elevated parietal cell antibody level without macrocytic anemia, iron deficiency, or vitamin B12 depletion." (PMID 37507704, 2023). "PPI treatment led to reduction in serum gastrin but did not cause iron deficiency." (PMID 35845020, 2020).
lung carcinoma (9 papers, 2013 to 2025). "Since the lungs and cells that make up the digestive apparatus and that secrete gastrin and other hormones produced in the stomach have the same embryological origin (endoderm), some studies have investigated if there is an association between HP infection and lung cancer." (PMID 37927631, 2023). "Studies have shown that H. pylori infection in lung cancer patients is accompanied by significantly elevated gastrin levels in plasma and tumor tissues, as well as increased cyclooxygenase-1(COX-1) and cyclooxygenase-2(COX-2) expression." (PMID 39434880, 2024). "Gastrin may contribute to lung cancer by inducing bronchial epithelial mucosal cell proliferation, atrophy, and induction of COX-2." (PMID 39434880, 2024). "In fact, gastrin levels are elevated in lung cancer tissues." (PMID 39434880, 2024). "High levels of gastrin have been correlated with the poor prognosis of lung cancer patients." (PMID 32286381, 2020). "Gastrin could contribute to lung cancer by inducing higher mucosal cell proliferation of bronchial epithelium to atrophy and induction of COX-2." (PMID 26316939, 2013). "Gastrin exerts a growth promoting effect on several gastrointestinal cancer cells and a variety of neoplasms that express CCKBR, including neuroendocrine, pancreatic, medulla thyroid and lung cancer." (PMID 28109268, 2017).
medullary thyroid carcinoma (9 papers, 2011 to 2023). "It should be noted that application of the NEP inhibition approach has been recently shown to improve the diagnostic sensitivity of radiolabeled gastrin in medullary thyroid cancer patients." (PMID 33114537, 2020). "In this sense, a model of metastatic medullary thyroid cancer has been successfully used to evaluate the diagnostic and therapeutic potential of radiolabeled gastrin directed to target CCKB receptor-expressing tumors in vivo." (PMID 26258070, 2015). "NCT02088645 aims to investigate 177Lu-PP-F11N, a gastrin analog, for imaging and therapy in patients with advanced medullary thyroid carcinoma (MTC), as well as gastroenteropancreatic-neuroendocrine tumors (GEP-NET) and NETs of the lung or thymus." (PMID 39380959, 2023). "Cholecystokinin-2 receptor is, for instance, of particular interest, especially in medullary thyroid carcinoma, and can be specifically targeted with gastrin-derived peptides." (PMID 37376181, 2023). "Using this approach, a collection of radiolabeled peptides derived from gastrin and cholecystokinin families showed anti-tumoral activity in xenograft models of medullary thyroid cancer [also extensively reviewed in Ref." (PMID 26258070, 2015). "Even though improved diagnostic efficacy during single NEP inhibition has been recently confirmed for a biodegradable radiolabeled gastrin analog in medullary thyroid carcinoma patients, the clinical translation of this concept in the case of NT radioligands would require dual ACE/NEP inhibition." (PMID 37958525, 2023). "The first results of using such an over-the-counter NEP-inhibitor drug (racecadotril) in combination with biodegradable radiolabeled gastrin in medullary thyroid cancer patients have been recently reported and strongly support the clinical applicability of this concept." (PMID 32526874, 2020). "This hypothesis would, in fact, be consistent with the observation that significant toxicity was observed in a human clinical trial of a 90Y-labelled mini-gastrin peptide for radiotherapy of medullary thyroid cancers." (PMID 26910279, 2016). "Gastrin acts as a potent cell-growth factor and has proliferative effects on various malignancies including gastric, colorectal, pancreatic, medullary thyroid cancers and small cell lung cancer, as well as tumors of the central and peripheral nervous systems through CCKBR." (PMID 21205300, 2011).
pernicious anemia (9 papers, 2012 to 2026). Megaloblastic anemia caused by vitamin B-12 deficiency due to impaired absorption. "In contrast, the plasma gastrin concentration varies considerably in fasting patients with chronic achlorhydria (as in pernicious anemia with preserved antral mucosa) from 100 to 2000 pmol/L." (PMID 34209478, 2021). "Aside from the lab values showing pernicious anemia with low B12 levels as well as elevated gastrin levels, this tumor is often asymptomatic or presents with nonspecific abdominal pain." (PMID 31106093, 2019). "Furthermore an increased gastrin concentration in fasting patients is observed in patients with pernicious anaemia or on proton pump inhibitor medication." (PMID 24213225, 2012). "Gastrin concentrations in fasting ulcer patients treated with PPI drugs are moderately increased, i.e., most levels reported are in between those of normal subjects and those of patients with severe long-term achlorhydria in pernicious anemia." (PMID 34209478, 2021).
Anxiety (8 papers, 2011 to 2026). Intense feelings of nervousness, tension, or panic often arise in response to interpersonal stresses. "The amygdala plays a key role in fear and anxiety and Cckbr knock-out mice are less anxious than normal mice, implying a possible role of Gastrin signaling between the MPA and the amygdala." (PMID 21858037, 2011). "Evidence has demonstrated that gastrin‐releasing peptide, whose release is mediated by PPI‐induced secretion of gastrin, plays a role in regulating aspects of behavior that could be modified in conditions including anxiety and depression." (PMID 40365732, 2025). "CCKBR is a G protein-coupled receptor for gastrin and cholecystokinin (CCK), which primarily regulates anxiety, feeding, and locomotion in the brain." (PMID 29770110, 2018).
chronic gastritis (8 papers, 2019 to 2026). Inflammation of the stomach that is chronic in nature. "Chronic gastritis caused by the H. pylori infection usually shows high levels of gastrin expression." (PMID 39234535, 2024). "This study evaluated the diagnostic efficacy of combining pepsinogen (PG I/II), gastrin-17 (G-17), and 13C-urea breath test (13C-UBT) for chronic gastritis in children using logistic regression and receiver operating characteristic (ROC) analysis." (PMID 41473911, 2025). "Gastrin-17 (G-17), a precursor of gastrin, may signal disease progression of chronic gastritis toward pre-cancerous lesions when elevated." (PMID 41473911, 2025). "The mechanism through which H. pylori infection induces GC mainly involves chronic gastritis, releasing gastrin and histamine, damaging DNA, and activating the proliferation of gastric epithelial cells through multiple pathways such as the induction of the PI3K/Akt pathway." (PMID 38195483, 2024). "The correlation between osteoporosis and chronic gastritis may be due to the ability of parathyroid hormone to stimulate gastrin secretion, as well as an increased pro-inflammatory profile in patients with chronic gastritis, which stimulates bone resorption." (PMID 37958752, 2023).
type 2 diabetes (8 papers, 2011 to 2025). "This study aims to determine the role of intestinal Gastrin/CCKBR on glucose absorption in the development of type 2 diabetes (T2D)." (PMID 39950948, 2025). "Taken together, our results support the notion of employing gastrin as a possible treatment for patients with type 2 diabetes." (PMID 31430329, 2019). "Moreover, they are also suggested as an adjuvant therapy for patients with type 2 diabetes, supposedly because they elevate plasma gastrin and thereby improve insulin secretion." (PMID 25993003, 2015). "The gastrin/CCKBR axis inhibits the expression of SGLT1 and GLUT2 through the PI3K/AKT/eIF4B signaling pathway, thereby preventing type 2 diabetes." (PMID 40733369, 2025). "Both type 2 diabetes (two at SND1–PAX4 locus and one at GAST locus) and GC (EFNA1, PTGER4 and PSCA loci) shared three significant variants after Bonferroni’s correction (P < 8.6 × 10−6) with PUD or its subtypes." (PMID 38036781, 2023).
breast carcinoma (7 papers, 2018 to 2025). "However, CRC differs from breast cancer in that it is affected by intestinal C. perfringens along with PPIs and gastrin in the blood." (PMID 32485921, 2020). "Moreover, miR-30a-3p acts as a promising suppressor gene by negatively regulating GAST expression and targets ANLN in breast cancer." (PMID 41361055, 2025).
gastric polyps (6 papers, 2008 to 2026). "Predictive value of pepsinogen (PG), gastrin-17 (G-17), and blood groups for differentiating solitary/multiple gastric polyps (GPs) and their size." (PMID 41578600, 2026). "The elevated reporting odds ratios (RORs) observed for “elevated blood gastrin,” “gastric mucosal hypertrophy,” and “gastric polyp bleeding” in this study provide pharmacovigilance support for this biological mechanism." (PMID 41488078, 2025). "Gastrin is a growth hormone, and concerns have been raised regarding its potent trophic effects: gastric polyp formation and potential progression to dysplasia following long-term acid suppression." (PMID 38139847, 2023). "Similar pathophysiological mechanisms may underlie the high reporting odds ratio (ROR) signals observed for blood gastrin increased, gastric mucosal hypertrophy, gastrointestinal polyp hemorrhage, and gastric polyps." (PMID 41488078, 2025). "Although the clinical significance of elevated fasting gastrin levels has not been fully determined, they have a well-documented association with both ECL hyperplasia and increased risk of gastric polyps in humans, especially fundic gland polyps (FGPs)." (PMID 38139847, 2023).